MFAP5 (microfibril associated protein 5)
Description:
May play a role in hematopoiesis. In the cardiovascular system, could regulate growth factors or participate in cell signaling in maintaining large vessel integrity (By similarity). Component of the elastin-associated microfibrils.
Synonyms: MFAP-5; MAGP-2; MAGP2; MP25; AAT9
Tractability: Antibody: its Gene Ontology location is reachable by antibodies, with high confidence; UniProt places it where antibodies can reach, with medium confidence; UniProt predicts a signal peptide or a membrane-spanning region.
Gene: Protein-coding gene on chromosome 12 (8,637,346 to 8,672,519, reverse strand). Ensembl gene ENSG00000197614.
Subcellular location: Secreted, extracellular space, extracellular matrix
Pathways (Reactome):
Extracellular matrix organization: Elastic fibre formation; Molecules associated with elastic fibres
Gene Ontology:
Molecular function: extracellular matrix structural constituent; microfibril binding
Biological process: definitive hemopoiesis; embryonic eye morphogenesis
Cellular component: extracellular matrix; extracellular region; microfibril; non-collagenous component of interstitial matrix
Genetic constraint (gnomAD): Loss-of-function variants: 20 observed, 29.81 expected, observed/expected ratio (o/e) 0.67, 90% interval 0.47 to 0.98. The upper end of that interval is the gene's LOEUF score, 0.98, which puts it in group 4 of 6, group 1 being the genes least tolerant of losing a copy. Missense variants: 195 observed, 207.65 expected, observed/expected ratio (o/e) 0.94, 90% interval 0.83 to 1.06. Synonymous variants: 86 observed, 71.35 expected, observed/expected ratio (o/e) 1.21, 90% interval 1.01 to 1.44.
Gene-disease validity (ClinGen):
ClinGen rates the evidence that MFAP5 causes each of these diseases.
familial thoracic aortic aneurysm and aortic dissection (autosomal dominant): Moderate. A rare genetic vascular disease characterized by the familial occurrence of thoracic aortic aneurysm, dissection or dilatation affecting one or more aortic segments (aortic root, ascending aorta, arch or descending aorta) in the absence of any other associated disease.
Homologues: Orthologues: chimpanzee MFAP5 (99% identical), macaque MFAP5 (96% identical), rabbit MFAP5 (82% identical), pig MFAP5 (82% identical), rat Mfap5 (77% identical), mouse Mfap5 (76% identical), dog MFAP5 (76% identical), tropical clawed frog mfap5 (32% identical), zebrafish mfap5 (25% identical). Paralogues in human: MFAP2 (28% identical).
Diseases named in the same sentence as MFAP5 in open-access papers:
MFAP5 is named in the same sentence as 70 diseases in open-access papers, as found by Europe PMC text mining. Sharing a sentence is not in itself a finding about the gene and the disease. The quoted sentences say what the papers report.
ovarian carcinoma (21 papers, 2013 to 2025). A malignant neoplasm originating from the surface ovarian epithelium. "The high expression level of MFAP5 (microfibrillar-associated protein 5) induces the ovarian cancer resistance of paclitaxel and cisplatin." (PMID 39003454, 2024). "MFAP5 was reported overexpressed in CAFs in ovarian cancer, and was associated with malignant tumor progression and chemoresistance of ovarian cancer, prostate cancer and cholangiocarcinoma." (PMID 37156839, 2023). "A study on ovarian cancer chemoresistance showed that CAFs increased the expression of lipoma-preferred partner (LPP) in endothelial cells through microfibrillar associated protein 5 (MFAP5)/FAK/ERK/LPP signaling pathway." (PMID 34095111, 2021). "In ovarian cancer, cancer-associated fibroblasts-derived MFAP5 upregulates lipoma-preferred partner (LPP) gene to enhance the efficacy of chemotherapy." (PMID 31775892, 2019). "MFAP5 (which was previously called: MAGP2, microfibril-associated glycoprotein 2) is a secretory protein which prolongs ovarian cancer cell survival, and increases endothelial cell motility, survival through the αvβ3 integrin receptor." (PMID 28881822, 2017). "Leung and colleagues showed that another member of the microdissected CAF-specific gene signature, microfibrillar-associated protein 5 (MFAP5), is a prognostic marker of poor survival rates in patients with ovarian cancer." (PMID 26751490, 2016). "However, high expression levels of MFAP5 are associated with a worse prognosis in ovarian cancer (both in epithelium and stroma)." (PMID 36531033, 2022). "Furthermore, siRNA- knockdown of TNNC1 abrogated the stimulatory effect of microfibrillar-associated protein 5 (MFAP5) on ovarian cancer cell motility, indicating TNNC1 as a downstream effector of MFAP5." (PMID 29416706, 2018). "MFAP5 has been closely related to the progression of gynecological diseases, such as breast cancer, ovarian cancer, cervical cancer, and uterine tumors." (PMID 38048229, 2023). "Further, MFAP5 was analyzed in human tissue samples of ovarian cancer, showing a higher mRNA expression in high-grade tumors, indicating a relationship between MFAP5 and rapid changes in matrix compositions." (PMID 37569268, 2023). "MFAP5 is a poor prognostic factor in ovarian cancer and its increased expression is correlated with microvessel density." (PMID 28881822, 2017). "CAF-derived MFAP5 induces F-actin cytoskeleton rearrangement and stress fiber formation in ovarian cancer cells." (PMID 26751490, 2016). "In addition, MFAP5 is crucial in regulating tumor progression in breast cancer, ovarian cancer and tongue cancer." (PMID 31775892, 2019). "Other researches also showed that MFAP5 mediates ovarian cancer cell motility and invasion potential through FAK/CREB/TNNC1 signaling pathways, suggesting that it may be a new modality of ovarian cancer treatment." (PMID 30899449, 2019). "MFAP5 expression was increased in head, neck, pancreatic, lung, and ovarian cancers." (PMID 27713166, 2017). "Several data suggest that MFAP5 may be involved in ovarian cancer progression." (PMID 36555638, 2022). "MFAP5 was an independent predictor of survival in advanced ovarian cancer, and could promote tumor proliferation and endothelial cell motility through αβV3 integrin mediated signaling, providing a potential mechanistic link between MFAP5 and angiogenesis as well as patient survival." (PMID 27713166, 2017). "In vivo, an intraovarian cancer cell injection model demonstrated that targeting stromal MFAP5 using siRNA delivered by nanoparticles significantly reduced tumor growth and metastasis, suggesting that targeting the CAF-derived secretory factor is a new treatment approach for ovarian cancer." (PMID 26751490, 2016).
breast carcinoma (17 papers, 2016 to 2025). "MFAP5 is a component of extracellular elastic microfibrils, implicated in cardiovascular progression, breast cancer, carcinogenesis, and alveolar elastogenesis." (PMID 37020143, 2023). "Increased MFAP5 expression in CAFs has been associated with tumor aggressiveness and poor survival in several cancer types, including ovarian, pancreatic, colorectal, and breast cancer." (PMID 41008788, 2025). "MFAP5 facilitated the proliferation and metastasis of breast cancer cell, as reflected by the elevated levels of matrix metalloproteinase 2 (MMP2) and MMP9 after MFAP5 overexpression." (PMID 39759103, 2024). "MFAP5 blockade can inhibit fibrosis and enhance chemosensitivity in ovarian and pancreatic cancer, and can promote basal-like breast cancer progression by activating epithelial-to-mesenchymal transition." (PMID 32457800, 2020). "In order to choose the proper BLBC cell lines, the MFAP5 level in human breast cancer cell lines BT20 and HS578T was analyzed." (PMID 30899449, 2019). "Some genes such as FGF18, FGFR2, ADAM12, NEDD9, MMP13 and CDC2 were also up-regulated in the related signaling pathway, which indicated that MFAP5 is indirectly involved in the regulation of various protein kinase pathways in breast cancer." (PMID 30899449, 2019). "However, some reports have demonstrated the role of MFAP5 in the progression of breast cancer 42, bladder cancer 43, colon cancer 44, and so on45." (PMID 40959103, 2025). "For example, MFAP5 may activate the epithelial–mesenchymal transition (EMT) program to promote basal-like breast cancer growth and aggressiveness." (PMID 39759103, 2024). "In addition, MFAP5 has been reported to promote basal-like breast cancer progression by activating the EMT program." (PMID 38136265, 2023). "Although there is evidence that MFAP5 expression in the stroma is associated with bladder and breast cancer malignant behavior, there is still a lack of direct evidence on how MFAP5 + fibroblasts mediate the remodeling of the TME in CRC." (PMID 37344903, 2023). "Besides the role played by ITGA5 in promoting breast cancer cell adhesion, invasion, and survival, EFEMP2, KIAA1199, and MFAP5 also enhance breast cancer motility and invasiveness." (PMID 33420367, 2021). "Moreover, another member of the microfibrillar-associated proteins, MFAP5, has also been implicated in the activation of the ERK signaling pathway in breast cancer cells." (PMID 34445187, 2021). "In addition, MFAP5 is upregulated in human breast cancer bone metastases compared to primary tumors." (PMID 33420367, 2021). "Next, we examined the function of MFAP5 in breast cancer cells." (PMID 30899449, 2019). "Moreover, MFAP5 regulates the progression of ovarian cancer, breast cancer, and tongue cancer." (PMID 37020143, 2023). "In breast cancer, CAF‐derived MFAP5 affects the invasion and migration of tumour cells through the Notch1/slug pathway." (PMID 36855786, 2023). "MFAP5 is involved in maintaining vessel integrity and also reported to promote epithelial-mesenchymal transdifferentiation (EMT) program in basal-like breast cancer." (PMID 36136606, 2022).
pancreatic cancer (8 papers, 2020 to 2025). "One study showed that CEACAMs are prognostic markers for some malignancies, including ccRCC, while another study showed MFAP5 to be involved in cancer-associated fibroblast activation in pancreatic cancer." (PMID 40699854, 2025). "MFAP5 is associated with poor prognosis in cancers like ovarian and intrahepatic cholangiocarcinoma, and high MFAP5 expression in CAFs correlates with unfavorable outcomes in pancreatic cancer." (PMID 40430018, 2025). "The CCLE dataset revealed elevated expression of six module genes (GFPT2, MFAP5, CTSK, MMP2, FSTL1, and PRRX1) associated with poor overall survival in patients with pancreatic cancer." (PMID 40430018, 2025). "These authors observed that the MFAP5 blockade reduced fibrosis, induced tumor vessel normalization and increased paclitaxel bioavailability in mice models of ovarian and pancreatic cancer." (PMID 36555638, 2022). "For example, targeting of gene MFAP5 was recently found to enhance chemosensitivity in ovarian and pancreatic cancers." (PMID 34283835, 2021). "In conclusion, our study successfully identified a module of six key genes—GFPT2, MFAP5, CTSK, MMP2, FSTL1, and PRRX1—through Weighted Gene Co-expression Network Analysis (WGCNA) to assess cancer-associated fibroblast (CAF) infiltration in pancreatic cancer (PC)." (PMID 40430018, 2025). "Utilizing the CCLE database, it was confirmed that fibroblast cell lines exhibited elevated mRNA levels of the six module genes (GFPT2, MFAP5, CTSK, MMP2, FSTL1, and PRRX1) (accessed on 2 March 2025) compared to pancreatic cancer cell lines." (PMID 40430018, 2025). "To further identify roles of MFAP5 in CAFs, we extracted and cultured human primary CAFs (CAF3) derived from the PDAC patient, and mouse primary CAF cell line (ImdyCAF) derived from spontaneous pancreatic tumors in transgenic mouse (KrasLSL-G12D, Trp53LSL-R172H, Pdx1-Cre (KPC) mice)." (PMID 37156839, 2023).
cervical cancer (5 papers, 2019 to 2024). A primary or metastatic malignant neoplasm involving the cervix. "Another study has found that MFAP5 silencing resulted in apoptosis and growth inhibition in cervical cancer cells." (PMID 39759103, 2024). "MFAP5 is a suppressor of oral tongue squamous cell carcinoma and cervical cancer." (PMID 36103219, 2022). "MFAP5 modulated EMT-related pathways, which led to a reduction in cervical cancer cell migration and invasion." (PMID 39759103, 2024).
bladder cancer (4 papers, 2021 to 2025). "Other studies have suggested that MFAP5 in the stroma is associated with cancer invasion in breast and bladder cancers." (PMID 37344903, 2023). "Microfibrillar-associated protein 5 (MFAP5) was reported to facilitate the proliferation and invasion of bladder cancer cells in vivo and in vitro experiments." (PMID 37784082, 2023). "Targeting MFAP5 can prove to be a new diagnostic and therapeutic method for bladder cancer treatment." (PMID 33808627, 2021).
intrahepatic cholangiocarcinoma (4 papers, 2022 to 2026). A carcinoma that arises from the intrahepatic bile duct epithelium in any site of the intrahepatic biliary tree. "Intrahepatic cholangiocarcinoma (ICC) patients with a higher level of MFAP5 are more likely with malignant progression and low survival rates." (PMID 35965507, 2022). "HIPPO/YAP1 signalling is also implicated in Ang II-mediated proliferation in intrahepatic cholangiocarcinoma (iCCA), with ARBs disrupting AGTR1+ cancer-associated fibroblast (CAF) MFAP5/Notch1 signalling by impeding YAP/TEAD nuclear translocation and reducing tumour proliferation." (PMID 41408463, 2026). "In intrahepatic cholangiocarcinoma (iHCC), losartan reduced stromal density by inhibiting YAP1/LAT1 dephosphorylation and MFAP5-mediated Notch1 signalling from AT1R+ CAFs." (PMID 41408463, 2026).
aortic aneurysm (3 papers, 2019 to 2025). A ruptured aneurysm located in the wall of the proximal portion of the descending aorta proceeding from the arch of the aorta. "Mutations in Microfibril-Associated Protein 5 (MFAP5), a member of the MGAP family, are linked to aortic aneurysms and dissections." (PMID 32486169, 2020).
cholangiocarcinoma (3 papers, 2018 to 2019). A carcinoma that arises from the intrahepatic biliary tree (intrahepatic cholangiocarcinoma) or from the junction, or adjacent to the junction, of the right and left hepatic ducts (hilar cholangiocarcinoma). "YAP/TEAD regulate pro-angiogenic microfibrillar-associated protein 5 (MFAP5) transcription in cholangiocarcinoma cells." (PMID 31052445, 2019). "Also, YAP activation is correlated with high MFAP5 expression in both human cholangiocarcinoma and cholangiocarcinoma xenografts." (PMID 31052445, 2019). "Moreover, in human cholangiocarcinoma (CCA), YAP signaling activated MFAP5 secretion to promote tube formation of human microvascular endothelial cells." (PMID 31775892, 2019).
osteoporosis (3 papers, 2021 to 2024). A condition of reduced bone mass, with decreased cortical thickness and a decrease in the number and size of the trabeculae of cancellous bone (but normal chemical composition), resulting in increased fracture incidence. "Molecular investigations have revealed that MFAP5 activates the Wnt/β-catenin signaling pathways, promoting osteogenic differentiation in osteoporosis." (PMID 39749331, 2024). "Then the RNA-seq verification by using total RNAs isolated from the femurs of normal and ovariectomized Wistar rats indicated that MFAP5, CAMK2A, and RGS4 in the ceRNA network were closely associated with osteoporosis." (PMID 35680981, 2022). "MFAP5 expression was significantly decreased in the primary osteoblasts of the osteoporosis compared to osteoarthritis group." (PMID 34865619, 2021). "Through analyzing bioinformatic data, we found that MFAP5 expression was downregulated in BMSCs in osteoporosis patients." (PMID 34865619, 2021). "Besides, RNA-seq analysis verification of the target genes indicated that the expression of MFAP5, CAMK2A, and RGS4 was significantly changed in the OVX rats and is closely associated with osteoporosis." (PMID 35680981, 2022). "We examined the GEO database and found that MFAP5 expression in the BMSCs of osteoporosis patients was lower than in controls, implying that MFAP5 might play a role in BMSC osteogenic differentiation." (PMID 34865619, 2021). "MFAP5 regulates osteogenesis via Wnt/β‐catenin- and AMPK-signaling; MFAP5 may serve as a therapeutic target in patients with osteoporosis." (PMID 34865619, 2021).
ovarian tumor (3 papers, 2020 to 2023). "Another pre-clinical report showed that antibody targeting of the protein MFAP5 reduced fibrosis in ovarian tumors in mice and enhanced response to the chemotherapeutic agent paclitaxel." (PMID 37438818, 2023). "Stromal MFAP5 acting as a metastasis-promoting gene and targeting stromal MFAP5 significantly decreased ovarian tumor growth and metastasis in vivo." (PMID 38136265, 2023).
scleroderma (3 papers, 2023 to 2025). Scleroderma is a rare autoimmune connective tissue disorder characterized by abnormal hardening of the skin and, sometimes, other organs. "Immunostaining of the human scleroderma skin sections revealed that ECM protein MFAP5 were enriched in the interstitial spaces (white arrows) and the hypodermal interphase space between the dermis and dermal adipose tissue, where THY1 and COL1 co‐expressed." (PMID 39072821, 2025). "In the skin, this transcriptional signature was observed in fibroblasts from unwounded skin responsible for ECM homeostasis and in a fibroblast population that undergoes contraction in scleroderma as compared to healthy skin (PI16+MFAP5+PCOLCE2+)." (PMID 37277655, 2023). "This MFAP5 gene activity is also detected in SSF, as fibroplasia is a hallmark of scleroderma." (PMID 40971055, 2025).
thoracic aortic aneurysm (3 papers, 2019 to 2024). An aneurysm formed in the wall of the proximal portion of the descending aorta proceeding from the arch of the aorta. "MAGP-2 (MFAP5) haploinsufficiency has been linked to thoracic aortic aneurysms and dissections, most likely due to a dysregulation in TGF-β signaling." (PMID 35216218, 2022). "Loss function of MFAP5 inhibits bone loss in mice, whereas MFAP5 mutation is associated with the pathology of thoracic aortic aneurysms and dissections in human." (PMID 31775892, 2019).
Cerebral ischemia (2 papers, 2023 to 2025). Restriction of arterial blood supply to the brain associated with insufficient oxygenation to support the metabolic requirements of the tissue. "Among cytoskeletal elements, MFAP5 exhibited a local arrangement and morphological characteristics due to focal cerebral ischemia comparable to NF-L and MAP2." (PMID 40548074, 2025). "Immunosignals of tricellulin, MFAP5 and α-catenin were quantified along with signals from the cytoskeletal elements MAP2 and NF-L at the ischemic border zone of the neocortex and subcortex in brain tissues from mice subjected to 24 h of focal cerebral ischemia." (PMID 37569268, 2023).
colon cancer (2 papers, 2022 to 2025). "Significant loss of MFAP5 expression in colon cancer stroma may facilitate the difference between pseudoinvasive and true invasive tumors with a specificity of 75% and a sensitivity of 80% in colonic adenomatous polyps." (PMID 36531033, 2022).
colonic adenomatous polyps (2 papers, 2020 to 2022). "Indeed, MFAP5 (microfibril-associated protein 5) may facilitate the distinction between pseudo-invasive and true-invasive lesions among colonic adenomatous polyps." (PMID 32457800, 2020).
diabetes (2 papers, 2023 to 2024). "Western blot (WB) and immunofluorescence experiments revealed that MFAP5 plays a crucial role in the progression of CAVD in the context of diabetes, offering new insights into the disease mechanism." (PMID 39749331, 2024). "MFAP5 is overexpressed in diabetic mouse models, and diabetes-induced cartilage degeneration is decreased in gene knockouts." (PMID 37778719, 2023). "The findings imply that MFAP5 may also be involved in metabolism-related diseases, such as diabetes." (PMID 39749331, 2024).